ENSG00000199566
Synonyms: LOC124900322
Gene: Small nucleolar RNA gene on chromosome 12 (47,346,166 to 47,346,297, reverse strand). Ensembl gene ENSG00000199566.
Gene Ontology:
Biological process: RNA processing
Cellular component: nucleolus
Homologues: Paralogues in human: SNORA10 (85% identical), SNORA10B (85% identical), SNORA64 (55% identical).